IDO1 (indoleamine 2,3-dioxygenase 1)
Diseases named in the same sentence as IDO1 in open-access papers (continued):
Sharing a sentence is not in itself a finding about the gene and the disease.
tumor (continued). "Therefore, both IDO1 and IDO2 may play an important role in cancer by inducing tumor-immune tolerance through enzyme-dependent and enzyme-independent IDO-mediated immunosuppression." (PMID 37408267, 2023). "In addition, IDO1 is highly expressed in mregDCs across an array of human tumours, which might enable the identification of tumour‐specific mregDCs." (PMID 36808888, 2023). "Understanding the involvement of IDO1-orchestrated tumor promoting inflammation in specific tumor types may thus be consequential for predicting whether they will be more amenable to IDO1-specific inhibitors or whether more broad-based pan-inhibitors will be required for successful intervention." (PMID 37182174, 2023). "Evidence that direct depletion of kynurenine in vivo using PEGylated kynurenase recapitulates the anti-tumor effects of targeting IDO1, also bolsters the argument in favor of catabolites, and kynurenine in particular, as the mechanism of action through which IDO1 imposes T cell tolerance." (PMID 37182174, 2023). "Furthermore, in the MB49 orthotopic tumor model, we found that either inhibition of AhR, IDO1 or SLC7A5 could achieve synergistic effect with cisplatin." (PMID 37670034, 2023). "This suggests that the IDO1 may play a role in either tumour growth or tumour environment in BrCa." (PMID 37041200, 2023). "While current efforts are proceeding to account for the failure of selective IDO1 inhibitors to inhibit tumor growth, modulating other components of the kynurenine pathway or interacting systems could provide new avenues for identifying means of disrupting the inflammation–cancer link." (PMID 37296860, 2023). "Recently, accumulating studies reported the immune moderating role of IDO1 in TME; it causes anergy of effector T cells and NK cells by inducing Trp depletion and promotes Treg differentiation by Kyn accumulation, which ultimately leads to tumor immune evasion." (PMID 37296221, 2023). "Also, critical immune checkpoint genes such as LAG3, PDCD1LG2, CD274, IDO1, PDCD1, and CTLA4 were evaluated because these genes are activated when T cells identify and attach to associated proteins on other cells, such as certain tumor cells." (PMID 37876438, 2023). "Therefore, upregulated hsa-miR-23a-3p in IDO1 overexpressed OS cell lines may signal other cells through exosomes to shape the tumor microenvironment towards tumor survival." (PMID 37284323, 2023). "However, the temporal dynamics of IDO1 activation and therefore metabolite production in human immune cells after tumour resection are currently unknown." (PMID 35963900, 2023). "The IDO1/TDO dual inhibitors may become a new strategy for tumor immunotherapy." (PMID 37564938, 2023). "Besides immunoregulatory effects interfering with tumor immune surveillance, IDO1 and IL4i1 may have a direct influence on controlling cancer cell biology by modulating the composition of the metabolic environment." (PMID 37196768, 2023). "Therefore, infiltration of IDO1 macrophages may influence the immune system and inhibit tumor metastasis." (PMID 36248886, 2022). "Preclinical and clinical studies have indicated the potential of combining IDO1 inhibitors with immune therapies for the treatment of cancer, strengthening an interest in the discovery of novel dioxygenase inhibitors for reversing tumour-mediated immune suppression." (PMID 36145311, 2022). "However, AS-IV has been shown to downregulate IDO1 expression and inhibit Treg activity, which may restore tumor immunomodulatory effects and inhibit ULM growth." (PMID 36139584, 2022). "The poor outcome of the subclonal ANK1 mutation may be caused by upregulation of IL4I1, IDO1, IFNG and MAPK12 which showed potential roles in tumor immune evasion through accumulation of immunosuppressive cells such as regulatory T cells and myeloid derived suppressor cells." (PMID 35962343, 2022). "TAMs may play a dual role in tumor immunity through the IDO1-Kyn-AhR pathway." (PMID 35681736, 2022).
tumor (continued). "These latter authors focused on these two transporters in part because their co-expression correlates with poor outcome in a range of cancer types, but not if co-expressed with IDO1: perhaps this explains the small number of IDO1-expressing tumours in which the two transporters co-associate." (PMID 36286592, 2022). "Subclonal ANK1 mutation is related to adverse outcomes of CRC through increasing IL4I1, IDO1, IFNG and MAPK12, which may cause tumor immune escape through the accumulation of immunosuppressive cells such as regulatory T cells and myeloid derived suppressive cells." (PMID 35962343, 2022). "Thus, it is necessary to investigate the correlation between IDO1 expression and tumor prognosis." (PMID 36212460, 2022). "It would seem that tumours do not gain much by associating transporters with IDO1." (PMID 36286592, 2022). "Also, tumours may sense that [Trp] above 50 μM can inhibit IDO1 activity by a mechanism involving reversed sequence of binding of Trp and O2 to the enzyme." (PMID 36286592, 2022). "IDO1 activity is an important contributor to the prevention and suppression of autoimmune dysfunction since it promotes the differentiation of regulatory T cells (Tregs) and inhibits effector cell function; it is also a major factor in defence against invading micro-organisms and tumour cells." (PMID 35371018, 2022). "Hence, the immunogenic action of IFNγ may be inevitably accompanied by an elevated immune evasion mechanism (PD-L1, IDO1, and Arg1) in the tumor microenvironment, and a specific therapeutic combination may overcome this unwanted effect." (PMID 34385592, 2022). "At the beginning of this study, to investigate whether IDO1 promotes 4T1 growth in vivo, we constructed stable overexpression of IDO1 and interference with IDO1 in 4T1 cell lines and injected into the left second breast pad of Balb/C mice to construct a tumor transplantation model." (PMID 36550159, 2022). "Studies showed that IDO1 expression was strongly induced by interferon-γ in cell lines and associated with lower CD3+ and CD8+ T lymphocyte infiltration and CD57+ NK-cell infiltration in tumor specimens, which could be the mechanism of immune escape." (PMID 36212460, 2022). "Thus, the induction of IDO1 in NK cells could maintain the standard cytotoxicity against tumour cells." (PMID 35682852, 2022). "Therefore, IDO1 inhibitors might act also as immune adjuvants able to reprogram the correct inflammatory response and block tumor neo-vascularisation." (PMID 35408802, 2022). "Moreover, the association of W>F substitutants to IDO1 expression level was specific to tumours and not seen in normal tissues." (PMID 35264796, 2022). "Additionally, the expression of IDO1 in tumor tissue could be affected by different treatment methods, such as chemotherapy and immunotherapy." (PMID 36212460, 2022). "Therefore, targeting IDO1 in tumor cells could be a novel therapeutic strategy for IDO1-expressing tumors." (PMID 35997090, 2022). "Furthermore, IDO1 induces tumor angiogenesis in vivo by regulating the IFN-γ/IL-6 balance." (PMID 35681736, 2022). "In addition, ROS effectively disrupt the structure of the endosomal/lysosomal membrane, allowing Cas9/sgRNA to escape from the endosomal/lysosomal and transport to the nucleus for efficient IDO1 knockdown, reducing Treg cells to cluster in the tumor microenvironment." (PMID 36550159, 2022). "However, few studies on the correlation between IDO1 and tumor angiogenesis, and this regulatory effect’s specific signaling transduction pathway remains unclear." (PMID 35681736, 2022). "In this regard, it has been recently demonstrated that Kyn production by IDO1‐expressing cells suppresses ferroptotic cell death, thus suggesting that IDO1‐expressing cells in the TME may assist tumor progression also through the activation of a cell survival pathway." (PMID 36054818, 2022).
tumor (continued). "We also found that ANK1 (P = 0.0018), IL4I1 (P = 1.2e−12), IDO1 (P = 0), IFNG (P = 0)and MAPK12 (P = 2.2e−12) are positively correlated with PD-L1 expression in CRC cancer which has been reported to be associated with worse prognosis and counteract effect of tumor-infiltrating lymphocytes." (PMID 35962343, 2022). "In addition to the tumor cells, IDO1 is also expressed by immune-related cells." (PMID 35681736, 2022). "Similarly, the expression level of AhR in TAMs is regulated by IDO1 in tumor." (PMID 35681736, 2022). "Furthermore, the IDO1 mRNA and protein relative in tumor tissues was also significantly inhibited." (PMID 35872931, 2022). "Thus, immunotherapies inducing extensive inflammation at the tumor site might benefit from a combination with an IDO1 inhibitor medication, as exposing a tumor to immune recognition is of little utility if the immune system cannot effectively eliminate it." (PMID 36119020, 2022). "There are questions on whether epacadostat doses used in the ECHO-301 trial could effectively inhibit IDO1 activity in the tumor microenvironment and whether targeting multiple enzymes in the KYN pathway to control Try metabolism would benefit to these patients." (PMID 34422661, 2021). "Besides IDO1 and Arg 1, other amino acid degrading enzymes such as tryptophan 2,3-dioxygenase and arginase 2, has relevance in the regulation of tumor-induced immune tolerance, including the induction of an immunosuppressive tumor microenvironment." (PMID 34389039, 2021). "Besides, polyamines favor the immunosuppressive tumor microenvironment by rendering DCs immunosuppressive dependent on indoleamine 2,3-dioxygenase 1 (IDO1) and promoting M2 polarization in macrophages through inducing mitochondrial oxidative phosphorylation by eIF5A hypusination." (PMID 34439208, 2021). "Indeed, IDO1 is responsible for catabolism of tryptophan within a tumor microenvironment." (PMID 34946170, 2021). "In patients, CAR T cells targeting EGFRvIII in a phase I trial led to marked expansion of tumor-infiltrating T cells but also increased expression of inhibitory regulatory T cells and upregulation of immunosuppressive markers indoleamine 2,3-dioxygenase 1 (IDO1) and PDL1." (PMID 34976006, 2021). "The contemporaneous administration of OXA and CLANs IDO1 could achieve synergetic antitumor effects via promoting DC maturation, increasing tumor-infiltrating T lymphocytes as well as decreasing the number of regulatory T cells in a subcutaneous colorectal tumor model." (PMID 33918635, 2021). "The results showed that IDO1 mRNA expression was strongly induced in tumour-infiltrating cells of the HCC tumour, which might facilitate an antitumour immune reaction and the expression of IDO in tissue specimens of HCC patients significantly correlated with better recurrence-free survival rates." (PMID 34680327, 2021). "Moreover, targeting the IDO1/TDO2-kynurenine-AHR pathway to restore potent anti-tumor immune responses is an important goal of cancer immunotherapy, which might be highly relevant for HCC and cholangiocarcinoma therapy." (PMID 34075438, 2021). "Moreover, we were able to visualize dynamic IDO1 regulation in the mesenteric lymph nodes (MLNs), an off-tumor IDO1 target, where the percentage uptake of 11C-l-1MTrp accurately annotated the therapeutic efficacy of multiple combination immunotherapies in preclinical models." (PMID 34148865, 2021). "Interestingly, a completed phase I clinical study (NCT02048709) of the orally active IDO1 inhibitor navoximod (also referred to as GDC-0919 or NLG-919) demonstrated the ability of this drug to stabilise tumour progression in 36% of treated patients as a single agent." (PMID 34685679, 2021). "As a matter of fact, we analyzed the immunohistochemical expression of IDO1 only at the tumor cell level, but the Kyn/Trp ratio could be the result of the catalytic enzyme overexpression in other cells of the tumor microenvironment, such as the dendritic cells." (PMID 33922388, 2021).
tumor (continued). "Moreover, we found that the prominent lymphocytes infiltration was accompanied by the dominance of M2-type macrophage as well as abundant negative regulators (e.g., CTLA-4 and IDO1), which constituted a microenvironment preferentially toward pro-tumor activities and fostered tumor progression." (PMID 33796538, 2021). "Nonetheless, constitutive IDO1 expression in tumor cells is still a key factor to mediate immune evasion, and thus exploring the mechanism of up-expression may guide and pre-evaluate the efficacy of therapeutic approaches by targeting IDO1." (PMID 35003126, 2021). "Hence, IFN‐γ‐induced IDO‐1 production may play a significant role in immune surveillance against tumours." (PMID 34310018, 2021). "In summary, there may be some discrepancies in IDO1 expression profiles in different tumor types." (PMID 35003126, 2021). "Therefore, blocking the extracellular secretion of IDO1 may enhance the anti-tumor effect of PD-1 inhibitors." (PMID 33552086, 2020). "Moreover, stimulation of IDO1 and Trp breakdown also impacts on Trp availability for immune cells over time and leads to the accumulation of Trp metabolites such as the kynurenines, which can directly modulate anti-tumor immune responses." (PMID 32153576, 2020). "However, the mechanisms of the changes of tumor IDO1 expression after NCRT remain to be elucidated." (PMID 32733806, 2020). "Therefore, lnc-sox5 may serve as a modulator of IDO1 in tumor cells and can be a potential therapeutic target for cancers." (PMID 32083005, 2020). "Therefore, IDO1 overexpression in the tumor microenvironment intimately impairs patients' outcome and may serve as a future prognostic predictor and drug target." (PMID 32117235, 2020). "It was tempting to speculate that the tumor-immunosuppressive microenvironment can drive the loss of effector functions on CD8 T cells through their sustained IFN-γ production, which may promote IDO1 expression in CRC, as has been recently reported." (PMID 33425745, 2020). "Several interventions inhibiting IDO1 have been shown to decrease tumor growth and elicit an immune response in rodent tumor models but targeting IDO1 as a standalone treatment has often failed to cause tumor eradication and to prevent disease progression altogether." (PMID 33005623, 2020). "Therefore, IDO1 in endothelial cells might limit the influx of tryptophan from the blood to the tumour or generate tumour‐toxic metabolites, thus restricting tumour growth and contributing to survival." (PMID 32227579, 2020). "Furthermore, IDO1 was correlated with the expansion, recruitment, and activation of MDSCs in tumours;40 thus, the reduced expression of IDO1 following DCA treatment may have led to reduction of MDSC infiltration." (PMID 31819179, 2020). "IDO1 activation can inhibit the function of cytotoxic T cells by promoting cell cycle stagnation and apoptosis, and downregulate the natural killer cell receptors.Furthermore, IDO1 can also boost the activity of regulatory T cells to engage the tumor immune escape mechanism." (PMID 32733806, 2020). "Recent studies have shown that tumor-targeted delivery of small molecule inhibitors toward the IDO1 could efficiently reverse the tumor immunosuppression and then enhance the therapeutic efficacy of chemotherapy and other cancer treatment modalities by activating the host’s immune system." (PMID 34138248, 2020). "Considering tumour mutations can result in immunogenic neo‐antigens, which have also been correlated with responsiveness to a more effective response to immune therapy, we analysed IDO1 expression with TMB status and grouped patients into IDO1‐high and IDO1‐low and analysed their TMB status." (PMID 32227579, 2020). "IDO1 level could therefore also be a marker of an ongoing anti‐tumour immune response." (PMID 32227579, 2020). "Therefore, inhibition of MERTK and IDO1 produces an anti-tumor effect, which benefits the host." (PMID 32346605, 2020).
tumor (continued). "IDO1 levels were associated with aggressive clinico-pathologic features of the tumor such as extrathyroidal extension and multifocality, suggesting that disruption of antitumor immunity by IDO1 expression, and thus, infiltration of FoxP3+ Treg cells may contribute to tumor progression in PTMC." (PMID 33986723, 2020). "Besides immunologic-dependent procarcinogenic mechanisms mediated by IDO1, which are predominantly based on inhibition of T cell activation and facilitating immune evasion of tumor cells, little is known about immune-independent functions of IDO1 in carcinogenesis." (PMID 32380691, 2020). "Therefore, determining the clinical significance of tumor-cell expression of these immune-related factors, PD-L1, PD-L2, and IDO1, and exploring their predictive value in resected NSCLC specimens, could be clinically useful." (PMID 31163080, 2019). "Interestingly, IDO1 inhibitor 1-MT could partially eliminate the tumor-promoting activity of IFN-γ-primed AFMSCs in immunocompetent hosts and completely reverse their antitumor activity in immunocompromised hosts." (PMID 31149015, 2019). "In addition, IDO1 can also trigger other activators of anti-tumor immunity." (PMID 31195673, 2019). "Preclinical studies showed that the COX-2/mPGES1 pathway is able to promote tumor immune escape mechanisms by increasing the number of T regulatory cells and myeloid derived suppressor cells, as well as by driving increased expression of indoleamine 2,3-dioxygenase 1 and PD-L1 by cancer cells." (PMID 31881699, 2019). "However, besides this effect that would dampen IDO1-mediated immunosuppression, high levels of NO can combine with superoxide anion thus generating reactive nitrogen species that compromise both the activity and migration of T cells at the tumor site." (PMID 31354721, 2019). "Moreover, blockade of IL-4 resulted in overexpression of pro-inflammatory cytokines (CXCL10, IL-1β, IL-15, IL-10 and IL-6) and lower expression of immunosuppressive molecules (Foxo3, IDO1 and PD-L1) as compared to cryo-thermal eosinophils + tumour-bearing DCs group." (PMID 31519961, 2019). "Thus, blocking the activity of IDO1 is a potential strategy for tumor immunotherapy." (PMID 31195673, 2019). "Moreover, ARG1-derived products, i.e. polyamines, could directly contribute to the generation of tolerogenic DCs through IDO1 phosphorylation, thus sustaining the immunosuppressive tumor microenvironment." (PMID 31533831, 2019). "Therefore, new insight is definitely needed into the molecular mechanisms underlying the antitumor effects of Arg starvation in both host and tumor, which might facilitate the refinement of IDO1 inhibitory approaches in cancer immunotherapy." (PMID 31354721, 2019). "Additionally, other immunosuppression mechanisms may have outweighed the induced anti-tumor reactions, such as PD-L1 and IDO1 expression (found by RT-qPCR analysis) that may have been induced by IFN-γ elicited by immunotherapy." (PMID 30469401, 2018). "Thus, targeting the Kyn–AhR pathway (such as by inhibiting IDO1 in tumor-repopulating cell or AhR in CD8+ T cells) may enhance the efficacy of adoptive T cell therapy." (PMID 30068361, 2018). "In addition to immune checkpoints, other therapies targeting the immune system, such as the indoleamine 2,3-dioxygenase 1 (IDO1) inhibitor, tumor vaccines, oncolytic viruses, and NK cell Ig-like receptor (KIR) in combination with PD-1/PD-L1 blockade are also under development." (PMID 30519541, 2018). "Therefore, effects of tryptamine on IDO1 inhibition may contribute to a more effective tumor-reactive response by immune cells, which is considered part of a viable strategy for anticancer therapies." (PMID 29468141, 2018). "Similarly, recruitment and activation of tumor-infiltrating MDSCs and regulatory T cells, driven by expression of IDO1, could be successfully reversed by D-1MT in mice." (PMID 30186285, 2018).